TEP1 (telomerase associated protein 1)
Description:
Component of the telomerase ribonucleoprotein complex that is essential for the replication of chromosome termini. Component of the vault particle, which is a massive ribonucleoprotein complex that may play a role in cargo transport and signal transduction (By similarity). Responsible for the localizing and stabilizing vault RNA (vRNA) association in the vault ribonucleoprotein particle. Binds to TERC (By similarity).
Synonyms: TLP1; TP1; VAULT2; p240; TROVE1
Tractability: PROTAC: ubiquitination databases record sites on it; its protein half-life has been measured.
Gene: Protein-coding gene on chromosome 14 (20,365,667 to 20,413,501, reverse strand). Ensembl gene ENSG00000129566.
Subcellular location: Nucleus; Chromosome, telomere
Subcellular location (Human Protein Atlas): Nucleoplasm; Vesicles
Gene Ontology:
Molecular function: enzyme binding; protein binding; telomerase activity; RNA binding; telomerase RNA binding
Biological process: telomere maintenance via recombination; protein transport; DNA metabolic process; RNA-templated DNA biosynthetic process
Cellular component: cytoplasm; nuclear matrix; telomerase holoenzyme complex; ribonucleoprotein complex; chromosome, telomeric region; nucleus
Genetic constraint (gnomAD): Loss-of-function variants: 241 observed, 316.16 expected, observed/expected ratio (o/e) 0.76, 90% interval 0.69 to 0.85. The upper end of that interval is the gene's LOEUF score, 0.85, which puts it in group 3 of 6, group 1 being the genes least tolerant of losing a copy. Missense variants: 3,044 observed, 3,415.9 expected, observed/expected ratio (o/e) 0.89, 90% interval 0.86 to 0.92. Synonymous variants: 1,288 observed, 1,368 expected, observed/expected ratio (o/e) 0.94, 90% interval 0.9 to 0.99.
Homologues: Orthologues: chimpanzee TEP1 (99% identical), macaque TEP1 (95% identical), pig TEP1 (81% identical), rabbit TEP1 (78% identical), mouse Tep1 (75% identical), rat Tep1 (75% identical), dog TEP1 (72% identical), guinea pig TEP1 (72% identical), tropical clawed frog tep1 (36% identical). Paralogues in human: WDR17 (8% identical), WDR81 (7% identical), MAPKBP1 (7% identical), NWD1 (7% identical), WDR62 (6% identical), AHI1 (5% identical), WDR7 (5% identical), WDR27 (4% identical), POC1A (4% identical), POC1B (4% identical), WDR75 (4% identical), WDR5 (4% identical), and 14 more.
Diseases named in the same sentence as TEP1 in open-access papers:
TEP1 is named in the same sentence as 54 diseases in open-access papers, as found by Europe PMC text mining. Sharing a sentence is not in itself a finding about the gene and the disease. The quoted sentences say what the papers report.
malaria (45 papers, 2005 to 2025). Malaria is a serious and sometimes fatal disease caused by a parasite that commonly infects a certain type of mosquito which feeds on humans. "This study identified two alleles (TEP1*R2 and, TEP1*S1) in An. gambiae s.l from western Kenyaregions with different malaria endemicities." (PMID 35948910, 2022). "This obersavation suggests the TEP1*R3 allele has potential for consideration as candidate molecule for malaria transmission blocking through applictions such as gene drive systems." (PMID 36457004, 2022). "This study reveals minimal genetic differentiation and a low population structure of the TEP1 alleles in the highland and lowland regions of western Kenya with different malaria transmission patterns." (PMID 35948910, 2022). "Here we investigated the frequency and distribution of TEP1 alleles in wild-caught malaria vectors on the Kenyan coast." (PMID 36457004, 2022). "Our observation of the abundance of the P. falciparum fully susceptible TEP1*S1 allele shows that the area has a huge number of mosquitoes that are ready to transmit malaria." (PMID 36457004, 2022). "In that report, an allele of an immune factor TEP1 that is known to affect A. gambiae susceptibility to malaria parasites is also recruited to eliminate sperm in males that have DNA breakage due to irradiation." (PMID 30924861, 2019). "TEP1*R1 homozygous mosquitoes are refractory to the rodent malaria parasite P. berghei and have decreased susceptibility to the human malaria parasite P. falciparum." (PMID 31237887, 2019). "Although all alleles confer variable degrees of resistance to malaria parasites, TEP1*R1 confers the highest levels of resistance." (PMID 26861587, 2016). "Surprisingly, in spite of the common mechanism of TEP1 activation, distinct alleles of TEP1 mediate efficient removal of defective sperm and killing of malaria parasites." (PMID 26394016, 2015). "TEP1 is a highly polymorphic gene with four major alleles that differ in their capacity to kill or to resist malaria parasites—namely, the resistance-associated alleles R1 and R2 and the susceptibility-associated alleles S1 and S2." (PMID 26394016, 2015). "Additionally, the observed reduction in malaria transmission was linked to the increased expression of anti-Plasmodium immune genes, such as Thioester-containing protein 1 (TEP1)." (PMID 38716193, 2024). "Despite reports of TEP1 genetic variations in An. gambiae, the correlation between TEP1 allelic variants and transmission patterns in malaria endemic settings remains unclear." (PMID 36899431, 2023). "The distribution of TEP1 variants is currently unknown in Gambian vector populations, where malaria transmission has significantly declined but incidence remains heterogeneous." (PMID 36899431, 2023). "However, further studies should be carried out to investigate the implication of the current distribution of TEP1 alleles on vector competence and sporozoite rates in mosquito populations and the importance of TEP1 surveillance for malaria control." (PMID 35948910, 2022). "Low TEP1*R allele frequencies observed in these malaria-endemic areas in our study sites may be a product of selective pressures in the TEP1 gene resulting in functional variations that select." (PMID 35948910, 2022). "These factors may cause vectorial rearrangement exerting selection pressure that could change TEP1 allele frequencies and subsequently, efficient vectors could thrive and continue transmitting malaria." (PMID 35948910, 2022). "Furthermore, the distribution of the TEP1 allele in western Kenya regions with varying malaria transmission intensities is unknown." (PMID 35948910, 2022). "Specifically, TEP1 is known to inhibit the development of malaria parasite in the midgut of mosquitoes through ookinete lysis and melanization." (PMID 38582836, 2024). "The Anopheles secreted LRR proteins APL1C and LRIM1 are required for malaria ookinete killing in conjunction with the complement-like TEP1 protein." (PMID 38354186, 2024).
malaria (continued). "TEP1 binds to ookinetes of the rodent malaria parasite Plasmodium berghei triggering their lysis, and its knockdown (kd) in susceptible and resistant strains of An. gambiae results in a significant increase in oocyst numbers." (PMID 39149419, 2024). "Although TEP1 is also involved in the killing of ookinetes of the human malaria parasite P. falciparum, it seems that different P. falciparum strains exhibit different levels of susceptibility to TEP1 through mechanisms that are not completely understood." (PMID 39149419, 2024). "Studies have indicated that TEP1 plays a crucial role in mosquito resistance against malaria parasites." (PMID 39195607, 2024). "SPCLIP1 is required for the accumulation of TEP1 on microbial surfaces, a reaction that leads to lysis of malaria parasites." (PMID 38191283, 2024). "In An. gambiae, SPHs are regulators of TEP1 mediated immune response against malaria parasites and other microbial infections." (PMID 35967454, 2022). "In Anopheles gambiae, TEP1 exhibits allelic variations that alter vector competence and subsequently influence malaria infectivity." (PMID 35948910, 2022). "The LRR proteins APL1C and LRIM1 are known to form a ternary complex with the complement-like protein TEP1, and activity of all three components of the complex are required for killing of malaria parasites in the mosquito midgut 23,24." (PMID 35428783, 2022). "TEP1 is the key protein that mediates lysis of malaria parasites by binding to the surface of invading ookinetes." (PMID 33626094, 2021). "TEP1 is a homolog of the mammalian C3 complement factor secreted in the hemolymph where it can bind to malaria parasites, leading to their elimination through lysis and melanization." (PMID 32105779, 2020). "Bs exposure can reduce the vector competence of An. dirus to malaria parasites through upregulating Imd signaling pathway and enhancing the expression of TEP1." (PMID 32891162, 2020). "The complement-like protein thioester-containing protein 1 (TEP1) is a key factor in the immune response of the malaria vector Anopheles gambiae to pathogens." (PMID 31237887, 2019). "In particular, CLT4 and TEP1 act against the malaria parasite as agonists and antagonists, respectively." (PMID 31608103, 2019). "TEP1 is secreted and circulates in the mosquito hemolymph, where its activated cleaved form binds and eliminates malaria parasites." (PMID 28095489, 2017). "The complement-related protein TEP1, which helps kill malaria parasites, also labels damaged cells for removal during mosquito spermatogenesis and promotes male fertility in the malaria vector Anopheles gambiae." (PMID 26394016, 2015). "We demonstrate that during spermatogenesis TEP1 binds to and removes damaged cells through the same complement-like cascade that kills malaria parasites in the mosquito midgut." (PMID 26394016, 2015). "Thioester-containing protein 1 (TEP1) is a key immune factor that determines mosquito resistance to a wide range of pathogens, including malaria parasites." (PMID 26394016, 2015). "The complement C3-like protein TEP1 of the mosquito Anopheles gambiae is required for defense against malaria parasites and bacteria." (PMID 24039584, 2013). "In mosquitoes, in addition to triggering phagocytosis of bacteria and lysis of malaria parasites, TEP1 accumulation on microbial surfaces triggers the PO cascade leading to melanization." (PMID 24039584, 2013). "SPCLIP1 is required for accumulation of TEP1 on microbial surfaces, a reaction that leads to lysis of malaria parasites or triggers activation of a cascade culminating with melanization of malaria parasites and bacteria." (PMID 24039584, 2013). "We found that this new protein, named SPCLIP1, regulates the accumulation of TEP1 on malaria parasites and bacteria, and show that this can lead to distinct defense reactions including lysis and melanization of the pathogen." (PMID 24039584, 2013).
malaria (continued). "In the African malaria mosquito, the TEP1 protein that is homologous to mammalian complement factor C3 is shown to play a central role in mosquito immunity to malaria parasites and bacteria." (PMID 24039584, 2013). "Deciphering the molecular basis of the TEP1-mediated immune response is relevant to understanding the determinants of vector competence and a potential source of novel vector-based malaria control strategies." (PMID 23055931, 2012). "The malaria-transmitting mosquito, Anopheles gambiae, uses acomplement-like pathway to defend against Plasmodium parasites.The complement C3-like protein, TEP1, binds to the surface of invadingparasites, triggering their destruction and clearance." (PMID 21533217, 2011). "Upregulation of six selected immune genes was observed compared to controls, at least two of which (LRIM1 and TEP1) influence the development of malaria parasites." (PMID 20949079, 2010). "One of them, the complement-like protein TEP1, has recently been shown to bind to and mediate the killing of the rodent malaria parasite P. berghei by the mosquito A. gambiae." (PMID 15644136, 2005). "Therefore, the associations between the TEP1 immunity gene in Anopheles and Pfs47 in P. falciparum may be an important determinant of malaria infections and could be targeted in blocking malaria transmission in primary vectors efficient in transmitting malaria from a molecular perspective." (PMID 39994226, 2025). "Thus, we described a TEP that can negatively regulate TEP1 and affect malaria parasite growth within mosquitoes." (PMID 40170182, 2025). "A ternary immune protein complex comprised of two LRR proteins, APL1C and LRIM1, and a complement-like thioester protein, TEP1, is an essential component of Anopheles immune protection against infection with the model rodent malaria parasite, Plasmodium berghei." (PMID 38354186, 2024). "The distribution of TEP1 allele variants does not distinctly correlate with malaria endemicity pattern in The Gambia." (PMID 36899431, 2023). "More importantly, these findings may imply that TEP1 plays limited role in the heterogeneous prevalence of malaria in The Gambia." (PMID 36899431, 2023). "Earlier studies have shown that adaption of the circulating P. falciparum populations to TEP1-mediated killing in sympatric An. gambiae population may be a driving factor for endemicity of malaria in sub-Saharan Africa." (PMID 36899431, 2023). "Since TEP1 plays an important role in the killing of malaria parasites, we investigated whether TEP1 was involved in the melanization of CSPmut oocysts." (PMID 35680915, 2022). "Because we found that APL1C and LRIM1 are also required for full protection from fungus-dependent mortality, we tested whether the TEP1 complex partner required for killing of malaria parasites is also involved in antifungal protection." (PMID 35428783, 2022). "TEP1 is one of the most studied factors in the A. gambiae anti-Plasmodium defense as a Plasmodium antagonist that provides protection against both human and rodent malaria parasites, triggering immune responses that include lysis and melanization." (PMID 35025886, 2022). "Resistant and susceptible alleles of the TEP1 gene of An. gambiae explained resistance to some but not all strains of the human malaria parasite Plasmodium falciparum." (PMID 32463828, 2020). "We examined whether the natural anti-parasitic protein TEP1 can be harnessed to generate malaria resistant mosquitoes." (PMID 28095489, 2017). "Taken together, we propose that pleiotropic antagonism may drive the evolution of the TEP1 locus and shape the genetic makeup of resistance to Plasmodium in a major malaria vector." (PMID 26394016, 2015). "However, TEP1 function was only examined in the immune responses of females, which are responsible for malaria transmission." (PMID 26394016, 2015).
malaria (continued). "The mosquitoes' innate immune system is a significant factor that may influence the level of malaria infection; in particular the thioester-containing protein 1 (TEP1) targets malaria parasites for destruction during their initial invasion of the body cavity." (PMID 23055931, 2012). "For example, LRIM1, APL1C and TEP1 have aprominent role in mosquito defense against P. berghei, but of theseproteins only TEP1 has been shown to play a role in controlling infections withhuman malaria parasites, P. falciparum." (PMID 21533217, 2011). "Thus, Rel2 is regulating the expression pattern of many and diverse genes of the Anopheles innate immune system, among which at least two (LRIM1 and TEP1) have very strong anti-malaria activity." (PMID 18325105, 2008). "An. gambiae s.s. is an anthropophilic indoor malaria vector and is susceptible to P. falciparum, which may explain higher TEP1*S1/S1 frequencies unlike An. arabiensis that is zoophilic and an outdoor dweler which haboured TEP1*R2/S1 genotypes." (PMID 35948910, 2022). "Genotyping TEP1 in local vector populations is, therefore, critical for monitoring changes in abundance that could explain sporozoite rates and potential malaria prevalence in varying levels of endemicities and is a potential tool for developing vector control interventions." (PMID 35948910, 2022). "Here we investigated whether TEP1 can be used to create malaria resistant mosquitoes." (PMID 28095489, 2017). "A number of different putative pattern recognition receptors have been identified to play a role in TEP1-dependent defense against bacteria and malaria parasites raising the possibility that mosquitoes may also have multiple recognitions systems that can activate the TEP1 convertase." (PMID 24039584, 2013). "Based on their increased expression of antimicrobial peptides (AMPs) and other immune components such as TEP1, these cell populations may have a primary role in the hemocyte-mediated immune responses that limit bacteria or the recognition and killing of malaria parasites." (PMID 34318744, 2021). "Two Anopheles immune genes with protective function against malaria parasites in functional assays, APL1 and TEP1, display hallmarks of a coordinate selective sweep in A. coluzzii as compared to A. gambiae." (PMID 26633695, 2015). "What triggers therelease of mature TEP1 from the LRIM1/APL1C complex is important to understandinghow the mosquito complement pathway targets and eliminates malaria parasites." (PMID 21533217, 2011). "Although the APL1, Tep1, and LRIM1 genes have been characterized as anti-malaria defense factors, it is probable that these are more generic defense molecules." (PMID 21408087, 2011). "APL1C has recently been shown to complex with the anti-malaria Anopheles resistance protein LRIM1 to regulate the activation of and to stabilize the opsonin TEP1, leading to P. berghei tagging and killing." (PMID 21408087, 2011). "Rel2 regulates the expression of the antibacterial genes CEC1, GAM1, DEF1, CEC3, and key malaria parasite antagonists, LRIM1, TEP1, and TEP4 in An. gambiae." (PMID 18325105, 2008). "Using CRISPR/Cas9-based CTL4 knockout, we show that A. gambiae can mount melanization-based refractoriness to the human malaria parasite, which is independent of the TEP1 complement-like system and the major anti-Plasmodium immune pathway Imd." (PMID 35025886, 2022). "TEP1, TEP3, and TEP4 promote phagocytosis to limit Gram-positive and Gram-negative bacterial infections, and both TEP1 and TEP3 are able to bind to the surface of malaria parasites and activate lysis and melanization." (PMID 34054842, 2021). "However, TEP1 and the APL1 paralog APL1C, along with another LRR protein, LRIM1, form a ternary immune complex that is required for protection against the rodent malaria parasites, P. berghei and P. yoelii." (PMID 26633695, 2015).
malaria (continued). "Consequently, in subsequent research examining the role of the IMD pathway in TEP1-mediated melanization, which is negatively regulated by TEP15, it is essential to incorporate a range of malaria parasite infection densities and various developmental stages of the malaria parasite within mosquitoes." (PMID 40170182, 2025). "gambiae infected with human malaria parasites demonstrate that TEP1 does not recognize P. falciparum oocysts, suggesting that successfully invading P. falciparum ookinetes that initially evaded TEP1 and mosquito complement recognition are similarly protected during the oocyst stage." (PMID 34111228, 2021).